IL37 (interleukin 37)
Diseases named in the same sentence as IL37 in open-access papers (continued):
Sharing a sentence is not in itself a finding about the gene and the disease.
ankylosing spondylitis (19 papers, 2015 to 2025). An autoimmune chronic inflammatory disorder characterized by inflammation in the vertebral joints of the spine and sacroiliac joints. "Previous reports suggested that IL37 was involved in the development of various inflammatory conditions, including ankylosing spondylitis and rheumatoid arthritis." (PMID 31138840, 2019). "IL-37 level was significantly higher in patients with Guillain-Barre syndrome (GBS), ankylosing spondylitis (AS), and Graves' disease (GD) than in healthy controls, and the expression level of IL-37 was closely related to disease activity." (PMID 29805973, 2018). "These increased levels often occur during exacerbations of the diseases and correlate with biomarkers of disease activity, suggesting that the expression of IL37 corresponds to the disease activity of RA, ankylosing spondylitis (AS), Graves’ disease (GD), and SLE." (PMID 31861585, 2019). "Interleukin-37 (IL-37) has been known to play an immunosuppressive role in various inflammatory disorders, but whether it participates in the regulation of pathogenesis of ankylosing spondylitis (AS) has not been investigated." (PMID 25627863, 2015).
Arthritis (19 papers, 2014 to 2025). Inflammation of a joint. "Intra-articular injections of recombinant (rh) IL-37 or adenovirus encoding human IL-37 in mice with collagen-induced or streptococcal cell wall (SCW)-induced arthritis drive the downregulation of locally produced IL-17 and other Th17-related cytokines and ameliorate arthritic symptoms." (PMID 30871134, 2019). "The anti-inflammatory effect of human IL-37 has been demonstrated in various experimental disease models in mice.21, -23 Interleukin-37 has shown protective effects in arthritis models." (PMID 40970517, 2025). "For example, administration of IL-37 protects mice against experimental colitis, liver inflammation and experimental arthritis in vivo." (PMID 40970517, 2025). "And, IL-37 treatment ameliorates temporomandibular joint inflammation via inhibiting the expression of NLRP3 and IL-1β, which can be reversed by knockdown of IL-1R88." (PMID 36418383, 2022). "Previous studies conducted in murine models revealed the improvement of clinical features related to inflammation such as fatigue, arthritis, insulin resistance, and gouty arthritis after treatment with recombinant IL-37." (PMID 33652679, 2021). "On the other hand, IL-4, IL-10, IL-37, and IL-38 play the role of relieving inflammation to restrict arthritis, particularly A20." (PMID 32958016, 2020). "In the next section, we will review the therapeutic potential of IL-37 and IL-38 in the skin and joint inflammation." (PMID 30871134, 2019). "With regard to experimental arthritis, systemic and intra-articular administration of recombinant IL-37 was able to inhibit the development of synovitis by reducing pro-inflammatory cytokines and modulating Th17 cells." (PMID 30886947, 2017). "Next, we investigated whether under inflammatory conditions, early in the CiOA model, adIL-37 injection leads to IL-37 protein expression and functionality (reduction of joint inflammation)." (PMID 40970517, 2025). "Transcriptomic analysis revealed the potential pathways through which IL-37 regulates arthritis." (PMID 39684587, 2024). "In addition, IL-37, which indicates M2 polarization of macrophages and IL-38, induced anti-inflammatory effects in animal models of arthritis and THP-1 in vitro." (PMID 34440629, 2021). "We also assessed the impact of IL-37 on an MSU crystal-induced mouse arthritis model." (PMID 27863506, 2016). "In LPS-induced inflammation models, as well as an arthritis model and in macrophages, CXCL1 production is strongly decreased by IL-37." (PMID 34029331, 2021).
gout (17 papers, 2016 to 2025). A condition characterized by painful swelling of the joints, which is caused by deposition of urate crystals. "It has been well recognized that the main mechanism of IL-37 for limiting the inflammatory response caused by uric acid in gout is the alleviation of the release of proinflammatory cytokines and chemokines." (PMID 39065733, 2024). "IL-37 has been recognized recently as a significant member of the interleukin family associated with developing and treating gout." (PMID 38053999, 2023). "We aimed to investigate the association between IL-37 genetic variants, IL-37 plasma levels, and various clinical phases of gout." (PMID 37853488, 2023). "This, we have recently demonstrated by the identification of six individuals carrying four different rare variants in IL37 that present with a more severe clinical form of gout." (PMID 34034819, 2021). "The Gln allele of the CREBRF p.Arg457Gln variant associates with increased BMI but reduced risk of diabetes, the Ser allele of the IL37 p.Asn182Ser variant with gout, and the Western Polynesian-specific Leu allele of the ABCC4 p.Pro1036Leu variant with gout." (PMID 34719381, 2021). "Additionally, four rare genetic variants of IL-37 have been identified in gout patients, indicating a possible predisposition for the development of gout." (PMID 37853488, 2023). "Moreover, 15 genetic variants of IL-37 were identified and their associations with the clinical variants of gout were evaluated." (PMID 37853488, 2023). "Therefore, we aimed to investigate the link between plasma levels of IL-37 and genetic variants of IL-37 in relation to the development and progression of gout." (PMID 37853488, 2023). "In the last decade, several research groups have focused on IL-37 and its association with gout." (PMID 37853488, 2023). "However, four rare IL-37 variants were found in six gout patients: p.(A144P), p.(G174Dfs*16), p.(C181*) and p.(N182S), but none of them was found in healthy controls (HCs)." (PMID 34248996, 2021). "Furthermore, the detection of 15 genetic variants of IL-37 and their association with the clinical phases of gout indicates that underrepresentation of common variants in the IL-37 gene may potentially influence progression of gout." (PMID 37853488, 2023). "A positive correlation was noted between serum IL-37 level and serum uric acid in patients with gout (r = 0.382, p = 0.008)." (PMID 39065733, 2024). "We compared serum IL-37 levels between gout patients (n = 40, 63.0 ± 13.8 years) and controls (n = 30, 58.4 ± 12.0 years), measured by the ELISA method." (PMID 39065733, 2024). "In the DNA sequencing of IL-37 using molecular inversion probe resequencing in gout patients, detection of p.(N182S)(rs752113534) carrier status was identified as a potent genetic variant favoring the risk of gout." (PMID 39065733, 2024). "Consistently, IL-37 expression in serum and peripheral blood mononuclear cells (PBMCs) in gout patients was also significantly higher than in healthy controls." (PMID 39065733, 2024). "There is a lack of data on the relationship between HMG-CoA reductase inhibitors and IL-37 expression in the pathogenesis of gout." (PMID 39065733, 2024). "There is growing evidence that IL-37 inhibitors can suppress the inflammatory response in gout by inhibiting multiple inflammatory signaling pathways and modulating macrophages." (PMID 38053999, 2023). "To the best of our knowledge, we are the first to demonstrate an elevation of IL-37 in the plasma of tophaceous gout Caucasian patients." (PMID 37853488, 2023). "Here, we show that IL-37 is significantly elevated in the plasma of patients with intercritical and tophaceous gout." (PMID 37853488, 2023). "Plasma levels of IL-37 were significantly higher in asymptomatic hyperuricemic (p = 0.045), intercritical gout (p = 0.001), and chronic tophaceous gout (p = 0.021) cohorts when compared to control group." (PMID 37853488, 2023).
gout (continued). "Others showed elevation of serum IL-37 in gout patients, particularly in the active tophaceous gout and its association with the levels of C- reactive protein (CRP) and pro-inflammatory cytokines." (PMID 37853488, 2023). "We demonstrated the up-regulation of IL-37 levels across the clinical phases of gout: asymptomatic hyperuricemia, intercritical, and chronic tophaceous gout compared to control." (PMID 37853488, 2023). "Taken all together, we showed an elevation of serum IL-37 across the clinical phases of gout compared to controls." (PMID 37853488, 2023). "In the current study, we investigated the expression of IL-37 in patients with active and inactive gouty arthritis." (PMID 27863506, 2016). "In the current study, we assessed the preventive and therapeutic effect of recombinant human IL-37 (rhIL-37) in human and murine gout models." (PMID 27863506, 2016). "As IL-37 was identified in the diseased synovial tissue from patients with gouty arthritis, synovial cells containing both MLS and FLS were exposed to MSU in studies in vitro." (PMID 27863506, 2016). "First, IL-37 was demonstrated to be expressed in synovial tissue and chronic tophus in patients with gouty arthritis." (PMID 27863506, 2016). "Second, different gouty arthritis models were used to investigate the inhibitory effect of IL-37 in vitro and in vivo." (PMID 27863506, 2016). "In addition, patients with gout, especially those with an active gouty attack, had significantly higher IL-37 levels in the serum, PBMC, and synovial tissue, compared to healthy controls." (PMID 39065733, 2024). "Gout patients showed a higher serum IL-37 level, compared to controls (p < 0.001)." (PMID 39065733, 2024). "Second, we identified the difference in serum IL-37 expression between gout and controls." (PMID 39065733, 2024). "In addition, the IL-37 level in human synoviocytes or synovial tissue in gout was significantly higher than that in normal controls." (PMID 39065733, 2024). "Next, we evaluated whether serum uric acid levels and acute-phase reactants are related to serum IL-37 levels in gout patients." (PMID 39065733, 2024). "In addition, IL-37, an anti-inflammatory cytokine with an important role in gout, also functions via an interaction with SMAD3, a major intracellular signalling effector of TGF-β, further enforcing the importance of this signalling pathway in gout." (PMID 36850003, 2023). "This evidence supports the implication of IL-37 in the pathogenesis of gout." (PMID 37853488, 2023). "It is evident that IL-37 participates in the modulation of the immune response in gout arthritis; however, little is known about the role of the IL-37 gene variation in the pathogenesis of gout." (PMID 37853488, 2023). "Thus, IL-37 appears to be a relevant mediator in the pathogenesis of gout, and the recombinant form can be considered as a potential therapeutic agent to combat gouty arthritis." (PMID 34248996, 2021). "Diseased synovial lining from patients with active gouty arthritis contained small amounts of IL-37, whereas tissue around chronic tophus from patients with chronic tophaceous gout contained large amounts of IL-37." (PMID 27863506, 2016). "IL‐37 has a distinctive anti‐inflammatory effect against various pathogens and inflammatory diseases, including influenza virus, MERS‐CoV, coxsackievirus B3, gout, and rheumatic diseases." (PMID 40452816, 2025). "In addition, to verify the role of IL-37 in gout, THP-1 macrophages stimulated with recombinant IL-37 dose-dependently suppressed the activation of caspase-1 and IL-1β in MSU-induced inflammation." (PMID 39065733, 2024). "We also found the serum IL-37 level to be closely associated with the serum uric acid level but not with ESR and CRP in gout." (PMID 39065733, 2024). "Moreover, IL-37 inhibited the immune reaction induced by MSU crystals in human and murine gout models." (PMID 37853488, 2023).
gout (continued). "However, acute-phase reactants including erythrocyte sedimentation rate (ESR, mm/h) and C-reactive protein (CRP, mg/L) in gout patients were not related to serum IL-37 levels (p > 0.05 of both)." (PMID 39065733, 2024). "However, no published study has analysed IL-37 levels across the four clinical phases of gout: asymptomatic hyperuricemia, intercritical gout, gouty flares, and chronic tophaceous gout." (PMID 37853488, 2023). "We also assessed the effect of recombinant human IL-37 (rhIL-37) in different human and murine gouty models: a human monocyte cell line (THP-1), human synovial cells (containing macrophage-like and fibroblast-like synoviocytes), a peritoneal murine model of gout and a murine gouty arthritis model." (PMID 27863506, 2016).
acute coronary syndrome (16 papers, 2014 to 2023). Signs and symptoms related to acute ischemia of the myocardium secondary to coronary artery disease. "This study aimed to investigate the clinical significance of IL-37 in acute coronary syndrome and its underlying mechanism." (PMID 28039466, 2017). "As demonstrated by clinical and and pre-clinical studies in animal models, IL-37 participates in atherosclerotic disease and its levels are highly upregulated in acute coronary syndrome in which increased IL-37 levels are correlated with poor outcomes." (PMID 38140053, 2023). "In acute coronary syndrome, as an acute state of serious homeostasis breakdown, plasma IL-37 levels were shown to be lower than in the control and mostly below 40 pg/mL, which is consistent with the Q3 range values in this study." (PMID 36834391, 2023). "Elevated plasma IL‐37, IL‐18, and IL‐18BP levels are also observed in patients with inflammatory conditions, such as acute coronary syndrome, where NLRP3 is involved." (PMID 35429346, 2022). "The interleukin-37 (IL-37) concentration is highly upregulated in acute coronary syndrome and elevated IL-37 baseline is related to poor outcomes." (PMID 32016113, 2020). "IL-37 was found to be involved in the atherosclerosis-related diseases and increased in acute coronary syndrome." (PMID 25960620, 2015). "However, the exact role of IL-37 in the patients with acute coronary syndrome (ACS) remains to be elucidated." (PMID 31686988, 2019). "Because numerous research studies have confirmed the role of inflammation in acute coronary syndrome, the possible explanation for this contradiction is that IL-37 levels in plasma may correlate with the grade of inflammation rather than the disease status." (PMID 28781417, 2017). "The plasma level of interleukin-37 is elevated in patients with acute coronary syndrome, however, its function during the onset and progress of the disease remains unclear." (PMID 28039466, 2017). "The interleukin-37 level is significantly increased in acute coronary syndrome." (PMID 28039466, 2017). "Thus, we propose that interleukin-37 could be a biomarker predictive of mortality in acute coronary syndrome." (PMID 28039466, 2017). "IL-37 is found to be increased in patients with acute coronary syndrome but not investigated in patients after percutaneous coronary intervention (PCI)." (PMID 25960620, 2015).
Insulin resistance (16 papers, 2016 to 2025). Increased resistance towards insulin, that is, diminished effectiveness of insulin in reducing blood glucose levels. "The changes in expression of IL-37 and other IL-1 family cytokine members in adipose and liver tissue in patients with weight loss contributed to the improvement of insulin resistance and inflammations in these patients." (PMID 33028050, 2020). "The links between insulin resistance, IL-37, and TSH under aging conditions should therefore be searched within those circuits involving regulation via oxidative metabolism and SIRT1, but accounting for differences in cell and tissue specificities and phases of tissue remodeling." (PMID 35742902, 2022). "This, however, may not be a bad prognostic sign, taking into account the evidence that an increase in IL-37 occurs in conditions with increased insulin resistance, which in very old males, in spite of the presence of overt atherosclerotic disease, can be a sign of longevity." (PMID 34946413, 2021).
non-small cell lung carcinoma (15 papers, 2013 to 2025). A group of at least three distinct histological types of lung cancer, including non-small cell squamous cell carcinoma, adenocarcinoma, and large cell carcinoma. "Previous literature has shown that IL-37 inhibits invasion and metastasis in non-small cell lung cancer by suppressing the IL-6/STAT3 signaling pathway." (PMID 40444012, 2025). "The non-small cell lung cancer (NSCLC) patient’s potential IL-37 regulation mechanism is poorly understood." (PMID 36874133, 2023). "IL-37 also showed antitumor effects in mouse non-small-cell lung cancer model." (PMID 29805973, 2018). "IL-37 also showed antitumor effects in mouse model of non-small-cell lung cancer." (PMID 29805973, 2018). "In non-small cell lung cancer (NSCLC), the IDO1–kynurenine pathway fosters naïve T cell conversion into Tregs, while tumor-derived IL-37 polarizes macrophages toward a suppressive phenotype, correlating with elevated Treg presence and reduced NK activity." (PMID 41394821, 2025). "Moreover, in non-small cell lung cancer (NSCLC), IL-37 directly suppresses tumor proliferation and migration, and restrains tumor progression through immunomodulation and angiogenesis regulation." (PMID 41293155, 2025). "Interleukin-37 (IL-37), a newly identified member of the IL-1 family, has been known to play an immunosuppressive role in a variety of inflammatory disorders, but whether it participates in the regulation of pathogenesis of non-small cell lung cancer (NSCLC) has not been investigated." (PMID 26791086, 2016).